PAK1 (p21 (RAC1) activated kinase 1)
Diseases named in the same sentence as PAK1 in open-access papers (continued):
Sharing a sentence is not in itself a finding about the gene and the disease.
pancreatic cancer (38 papers, 2006 to 2025). "MUC13, a newly discovered transmembrane mucin that was found to be overexpressed in pancreatic cancer, is associated with dysregulation of PAK1." (PMID 35566098, 2022). "Although, as far as we are aware, this is the first study to examine HIF1α as a downstream effector of PAK1 in pancreatic cancer, PAK1 has previously been linked to HIF1α in colorectal cancer." (PMID 26774265, 2016). "Among the 72 primary pancreatic cancer patients, high PAK1 expression was associated with younger age (P = 0.038) and moderately or well differentiated tumor (P = 0.007)." (PMID 25182632, 2014). "However, the role of PAK1 in PD-L1 control has been shown more convincingly in pancreatic cancer models, where the loss of PAK1 decreased PD-L1 expression while increasing tumor infiltration by CD4+ and CD8+ T-cells." (PMID 37830586, 2023). "Our previous report demonstrated that using FRAX597 (PAK1 inhibitor) with gemcitabine produced the maximal inhibitory effect on tumour growth in an immunocompetent (C57BL/6) murine orthotopic pancreatic cancer model." (PMID 41294859, 2025). "The inhibition of PAK1 or PAK4 suppresses pancreatic cancer by stimulating anti-tumour immunity through the activation of T cells and dendritic cells through ICAM-1 and VCAM-1 upregulations." (PMID 41294859, 2025). "In pancreatic cancer, all three group I PAKs (PAK1–3), as well as each of group II PAKs (PAK4–5), except for PAK6, have been reported." (PMID 40001881, 2025). "The data showed that Pak1 is highly expressed in pancreatic tumor tissue (T = 179) when compared to the normal pancreatic tissue (N = 171)." (PMID 40090587, 2025). "In the expression study conducted by Han and his team in primary and metastatic pancreatic cancer tissues, lower PAK1 levels were detected in metastatic tissues than in primary tissues." (PMID 40864802, 2025). "Knockout of PAK1 or PAK4 increased the pericyte coverage in pancreatic tumour tissues by increasing the ratios of NG2 to CD31 and of α-SMA to CD31." (PMID 40943273, 2025). "Knockout of PAK1 and PAK4 suppressed pancreatic tumour growth, which was associated with a reduction in tumour vascularisation." (PMID 40943273, 2025). "Recent studies have consistently demonstrated Pak1 OE in pancreatic cancer, highlighting its involvement in promoting cell proliferation, migration, invasion, and resistance to chemotherapy." (PMID 40090587, 2025). "Altered PAK1 expression was associated with reduced survival in skin and prostate cancers, while PAK2 alterations were linked to poor outcomes in pancreatic cancer." (PMID 39756822, 2025). "Knockout of PAK1 or PAK4 suppressed pancreatic tumour growth in a syngeneic mouse model, demonstrated by reduced tumour volume and tumour weight." (PMID 40943273, 2025). "Exosome-derived miR-485-3p from normal pancreatic ductal epithelial cells inhibited pancreatic cancer metastasis by directly targeting PAK1." (PMID 37190165, 2023). "Our preliminary data from a comprehensive global proteomic analysis showed a substantial decrease in fibronectin levels in the PAK1 knockout (KO) pancreatic cancer cells." (PMID 38067120, 2023). "Shikonin, a natural inhibitor of PAK1, sensitises the pancreatic cancer cells to the chemotherapeutic drugs of gemcitabine and 5-FU." (PMID 38067120, 2023). "More importantly, inhibition of PAK1 deceased PD-L1 expression of pancreatic cancer cells and stimulated the antitumour immunity to suppress pancreatic cancer." (PMID 37537668, 2023). "The Dishevelled, EGL-10 and Pleckstrin (DEP) domain-containing protein 1B has been reported to promote pancreatic cancer cell motility and invasion via activation of the PAK1/LIMK1/Cofilin1 Signaling Pathway." (PMID 37190165, 2023). "We have previously reported that ATRA exerted synergistic effects with gemcitabine to inhibit pancreatic cancer via the downregulation of PAK1." (PMID 37537668, 2023).
pancreatic cancer (continued). "The benefits of co-targeting PAK1 signaling with other chemotherapeutic agents have also been shown to improve the therapeutic outcome of pancreatic cancers and decrease pancreatic cancer cell resistance to treatments." (PMID 37190165, 2023). "In the TME of pancreatic cancer, there is a positive correlation between PAK1 expression and the expression of α-SMA and Desmin, suggesting the potential involvement of cancer-associated fibroblasts (CAFs), which are known contributors to angiogenesis." (PMID 38067120, 2023). "Shikonin diminished PAK1 downstream signaling pathways, inhibiting proliferation and inducing apoptosis of pancreatic cancer cells." (PMID 35566098, 2022). "Increasing evidence shows that PAK1 is overexpressed in pancreatic cancer patients, and the deregulation of PAK1 contributes to increased cancer cell survival, proliferation, migration and Gem resistance." (PMID 35566098, 2022). "The results of this study revealed that PAK1 is a new target of shikonin, and that inhibition of the PAK1 downstream signaling pathways is a mechanism of shikonin-induced cytotoxicity in pancreatic cancer cells." (PMID 35566098, 2022). "In this study, the natural product shikonin was identified as a novel PAK1 inhibitor that significantly inhibited the growth and induced apoptosis of pancreatic cancer cells." (PMID 35566098, 2022). "PAK1 modulates pancreatic cancer cell transformation as well as an invasive EMT phenotype via the NF-κB/p65/fibronectin pathway." (PMID 36230657, 2022). "GCB in combination with gemcitabine has also been reported to reduce the growth of pancreatic cancer cells through the down-regulation of PAK1 and PAK4." (PMID 33567682, 2021). "As previously reported, circ_0066147 contributed to cell growth and metastasis via upregulating p21-activated kinase 1 (PAK1) through acting as a sponge for miR-330-5p in pancreatic cancer." (PMID 33832516, 2021). "The result indicated that the inhibition by cannabis oil of pancreatic tumour growth was blocked in PAK1 KO mice, suggesting that these cannabinoids suppressed pancreatic tumour growth in vivo via a PAK1-dependent pathway." (PMID 33126623, 2020). "We have recently reported that inhibition of PAK1 suppressed pancreatic cancer and stimulated the anti-tumour immunity of PC by down regulation of the expression of PD-L1 (a key target of immune checkpoint inhibition) by cancer cells." (PMID 33126623, 2020). "Inhibition of PAK1 suppresses PSCs activation and increases survival of mice with pancreatic cancer." (PMID 29967585, 2018). "p-21 activated kinase 4 (PAK4) is a gene that is recurrently amplified or overexpressed in PDAC and both PAK4 and related family member PAK1, have been linked to aberrant RAS activity, a common feature in pancreatic cancer." (PMID 27845911, 2017). "Elevated expression of PAK1 (p21-activated kinase 1) is frequently observed in various kinds of human cancers including colon or pancreatic cancers." (PMID 28423593, 2017). "Whilst in KRAS wild-type pancreatic cancer cell lines PAK1 overexpression led to increased colony formation." (PMID 27845911, 2017). "Considering that half of pancreatic cancers and more than 20% of colon cancers show deletion of Smad4, inhibition of PAK1 would be one of plausible strategy for treatment of human cancers such as pancreatic cancer and colon cancer." (PMID 28423593, 2017). "This study aimed to characterise the expression and functional relevance of PAK1 in pancreatic cancer." (PMID 26774265, 2016). "PAK1 is also up-regulated in pancreatic cancer cell lines when expression of MUC13, a transmembrane mucin, is increased." (PMID 26774265, 2016). "PAK1 KD inhibited pancreatic cancer cell growth and survival, and increased sensitivity to gemcitabine treatment." (PMID 26774265, 2016). "This study suggests the promise of inhibiting PAK1 function and defines areas for further investigation to clarify its potential value as a target for pancreatic cancer therapy." (PMID 26774265, 2016).
pancreatic cancer (continued). "PAK1 expression was measured in pancreatic cancer specimens by immunohistochemistry and in pancreatic cancer cell lines by western blotting." (PMID 26774265, 2016). "In all the pancreatic cancer cell lines tested, PAK1 activity was significantly decreased after treatment with FRAX597 alone, but no change in activity was observed after treatment with gemcitabine alone." (PMID 26774265, 2016). "Of the six isoforms, PAK1 is the best documented and has been found to be up-regulated in a number of cancers, including pancreatic cancer." (PMID 26774265, 2016). "PAK1 staining of pancreatic ductal adenocarcinoma cells was observed in all 10 human pancreatic cancer samples tested." (PMID 26774265, 2016). "Combination of a PAK1 inhibitor such as FRAX597 with cytotoxic chemotherapy deserves further study as a novel therapeutic approach to pancreatic cancer treatment." (PMID 26774265, 2016). "All pancreatic cancer cell lines showed upregulation of PAK1 compared to the normal pancreas cell line, HPDE, regardless of Kras mutational status." (PMID 26774265, 2016). "Knock-down experiments indicated that PAK1 is required for proliferation and survival of human pancreatic cancer cell lines through AKT- and/or HIF1α-dependent pathway(s)." (PMID 26774265, 2016). "PAK1 was expressed in all human pancreatic cancer samples tested, an7d was upregulated in all pancreatic cancer cell lines tested." (PMID 26774265, 2016). "Our IHC analysis of 72 primary pancreatic cancer samples and 20 liver metastatic samples revealed that PAK1 expression was lower in liver metastatic sites of pancreatic cancer compared to primary pancreatic cancer tissues." (PMID 25182632, 2014). "Among the total 92 cases, primary pancreatic cancer samples had a significantly higher rate (38/72, 52.8%) of high PAK1 expression than liver metastatic samples (5/20, 25.0%) (P = 0.028)." (PMID 25182632, 2014). "PAK1 protein expression was significantly higher in the 72 human primary pancreatic cancer tissues compared to the 20 liver metastatic tissues as determined by IHC." (PMID 25182632, 2014). "The relationships between PAK1 and clinicopathological parameters and prognosis in primary and metastatic pancreatic cancer were analyzed." (PMID 25182632, 2014). "Our study was the first to demonstrate high PAK1 expression in primary pancreatic cancer tissues compared to liver metastatic tissues of pancreatic cancer." (PMID 25182632, 2014). "The multivariate Cox model analysis identified PAK1 as a possible prognostic factor in pancreatic cancer patients." (PMID 25182632, 2014). "We report for the first time that PAK1 is a novel prognostic marker for pathologically confirmed human pancreatic cancer." (PMID 25182632, 2014). "In this study, we investigated PAK1 expression status and evaluated the prognostic significance of PAK1 in human pancreatic cancer." (PMID 25182632, 2014). "In univariate analysis for primary pancreatic cancer patients, PAK1 expression status (P = 0.004), differentiation (P = 0.017) and clinical stage (P = 0.001) were prognostic factors." (PMID 25182632, 2014). "The rate of high PAK1 expression in primary pancreatic cancer samples was twice as high as the rate in metastatic pancreatic cancer samples (52.8% vs 25.0%, respectively)." (PMID 25182632, 2014). "One study in a BALB/c mouse model of human pancreatic adenocarcinoma xenografts found overexpression of PAK1 in moderately to well differentiated pancreatic cancer samples." (PMID 25182632, 2014). "The rate of high PAK1 expression was significantly higher in primary pancreatic cancer samples (38/72, 52.8%) than in metastatic pancreatic cancer samples (5/20, 25.0%) (P = 0.028)." (PMID 25182632, 2014). "Univariate and multivariate analysis by Cox regression including PAK1 and other prognostic pathological markers demonstrated high PAK1 immunostaining as a prognostic factor for survival in pancreatic cancer patients (P < 0.005)." (PMID 25182632, 2014).
pancreatic cancer (continued). "A striking finding from our study was the correlation of high PAK1 expression with a better survival outcome in primary pancreatic cancer patients." (PMID 25182632, 2014). "We examined and scored the expression of PAK1 by immunohistochemistry in 72 primary pancreatic carcinoma samples and 20 liver metastatic samples." (PMID 25182632, 2014). "The present study investigated the clinical and prognostic significance of PAK1 expression in pancreatic carcinoma." (PMID 25182632, 2014). "Low PAK1 expression was detected in 34/72 (47.2%) pancreatic carcinomas, while high PAK1 expression was detected in 38/72 cases (52.8%)." (PMID 25182632, 2014). "We have also explored the impact of Pak1 specifically in the pancreatic cancer cell metabolism." (PMID 40090587, 2025). "As a result of the study, it was stated that the effect of PAK1 on pancreatic cancer metastasis may be low, and these findings suggest that it does not have the same effect in every tissue and its cellular functions may vary." (PMID 40864802, 2025). "We also speculated that the pathway could function in colorectal, colon, and pancreatic cancers, as PAK1 is overexpressed in these cancers." (PMID 36830998, 2023). "Recently, CP734, a PAK1 inhibitor, was reported to suppress pancreatic cancer growth in mouse." (PMID 36672500, 2023). "Besides, PAK1 inhibitors also significantly suppressed tumor invasion and metastasis of in situ xenograft models of human pancreatic cancer cell lines with GEM resistance." (PMID 35566098, 2022). "Using bioinformatics analysis, we analyzed previous high throughput datasets of GEM resistance, revealed their network relationships, and obtained the circLMTK2/miR-485-5p/PAK1 axis that might play a regulatory role in pancreatic cancer." (PMID 36059806, 2022). "The phosphorylation of RUNX3 by PAK1 promotes pancreatic cancer progression." (PMID 36230657, 2022). "Moreover, shikonin inhibited PAK1 activation and its downstream signaling pathway proteins, while reducing proliferation and inducing apoptosis of pancreatic cancer cells." (PMID 35566098, 2022). "Furthermore, our previous studies and those of others have shown that PAK1 is overexpressed in most pancreatic cancer tissue samples and specifically inhibiting or knockdown PAK1 reduced cell growth both in vitro and in vivo." (PMID 35566098, 2022). "Therefore, PAK1 is expected to be a potential target for pancreatic cancer treatment and chemotherapy sensitization, and the screening and development of specific inhibitors are of great significance." (PMID 35566098, 2022). "Furthermore, a recent study of 72 paraffin-embedded primary pancreatic cancer samples and 20 liver metastases from PDAC patients, reported that PAK1 expression was elevated in primary pancreatic cancer tissue compared with that taken from metastases." (PMID 27845911, 2017). "All human and murine pancreatic cancer cell lines tested expressed phosphorylated and total PAK1." (PMID 26774265, 2016). "Interestingly, these two pancreatic cancer cell lines had the lowest phospho-PAK1 expression of all the pancreatic cancer cell lines tested." (PMID 26774265, 2016). "Furthermore, PAK1 has been shown to regulate NFκB transcription upstream of fibronectin regulation in pancreatic cancer." (PMID 26774265, 2016). "Our finding that PAK1 is expressed in pancreatic cancer is in agreement with previous studies." (PMID 26774265, 2016). "In addition, reduced expression of PAK1 correlated with poor histological differentiation in pancreatic cancer and closely correlated with poorer OS." (PMID 25182632, 2014). "Additionally, PAK1 expression was lower in liver metastatic sites of pancreatic cancer compared to primary pancreatic cancer tissues." (PMID 25182632, 2014). "Nevertheless, the exact molecular mechanism by which PAK1 is involved in pancreatic cancer development and progression still remains unclear." (PMID 25182632, 2014). "Two recent studies examined PAK1 expression in pancreatic cancer." (PMID 25182632, 2014).
pancreatic cancer (continued). "Reduced expression of PAK1 correlates with poor histological differentiation in pancreatic cancer." (PMID 25182632, 2014). "Together these findings indicated that PAK1 may be a novel prognostic factor for survival in pancreatic cancer patients." (PMID 25182632, 2014). "Thus, further investigations of PAK1 expression in pancreatic cancer will be needed to elucidate the precise mechanism for its exact regulatory pathway in vitro and in vivo." (PMID 25182632, 2014). "This suggests that PAK1 may recognize a certain category of oncofetal antigens that are differentially expressed on pancreatic carcinomas." (PMID 25182632, 2014). "PAK1 may play a role in the resistance of pancreatic cancer to hypoxia through regulation of HIF1α." (PMID 26774265, 2016). "Furthermore, PAK1 knock-down sensitised pancreatic cancer cells to gemcitabine." (PMID 26774265, 2016). "Indeed, as shown in pancreatic cancer cells, EGF stimulation leads to tyrosine phosphorylation of Vav1, followed by the activation of a Rac1/Pak1/NF-κB signaling pathway resulting in an increase in cyclin D1 which leads to enhanced pancreatic tumor cell proliferation." (PMID 26353933, 2015). "However, the expression and clinical relevance of PAK1 expression in human pancreatic cancer remains unknown." (PMID 25182632, 2014). "Future studies integrating in vivo perfusion and pimonidazole assays will be valuable to validate the functional consequences of PAK1 or PAK4 modulation on vascular normalization and hypoxia in pancreatic cancer models." (PMID 41294859, 2025). "Amplifications in PAK1 and PAK2 were particularly prevalent in breast, lung, prostate, and pancreatic cancers, reinforcing their roles in tumorigenesis." (PMID 39756822, 2025). "Previous studies have demonstrated that PAK1 and PAK4 contribute to pancreatic cancer progression through diverse mechanisms, including the regulation of proliferation, angiogenesis, and immunity." (PMID 41294859, 2025). "The individual roles of PAK1 and PAK4 in pancreatic tumour biology are increasingly recognised, yet their distinct contributions to vascular regulation and chemotherapy response remain underexplored." (PMID 41228228, 2025). "P21-activated kinases (PAKs) are key regulators of the cellular and immune system, but the specific roles of PAK1 and PAK4 in pancreatic tumour vasculature and chemotherapy sensitivity are unclear." (PMID 41228228, 2025). "PAK1 and/or PAK4 are overexpressed in pancreatic cancer and play a crucial role in its progression, becoming a potential therapeutic target." (PMID 41294859, 2025). "Together, these results highlight the mechanisms through which PAK1 and PAK4 regulate the vasculature in pancreatic cancer, offering opportunities to exploit their differential functions for tailored therapeutic strategies." (PMID 41294859, 2025). "Inhibition of PAK1 also stimulated the intra-tumoral CD4+ and CD8+ T cells and suppressed pancreatic cancer." (PMID 36672500, 2023). "A PAK1 inhibitor, FRAX597, when combined with gemcitabine, led to a synergistic inhibition of pancreatic cancer proliferation in vitro and a further reduced tumour growth in vivo." (PMID 38067120, 2023). "In this context, our analysis of RNA-sequencing data from the human pancreatic cancer cell lines PANC1 and MIAPACA2 treated with a designed G4 ligand CM03 revealed downregulation of PAK1, PAK2, PAK4, and PAK6 mRNAs." (PMID 36830998, 2023). "P21-activated kinase 1 (PAK1), a serine/threonine protein kinase, is overexpressed in many cancers including breast, colon, prostate and pancreatic cancers." (PMID 37537668, 2023). "Therefore, PAK1 may serve as a potential therapeutic target for pancreatic cancer." (PMID 35566098, 2022). "The model simulations proposed the proteins AURKA, CD44, PAK1, STAT3, and TWIST1 as promising therapeutic targets for pancreatic cancer." (PMID 33578795, 2021).